GGT1 (gamma-glutamyltransferase 1)
Description:
Cleaves the gamma-glutamyl bond of extracellular glutathione (gamma-Glu-Cys-Gly), glutathione conjugates (such as maresin conjugate (13R)-S-glutathionyl-(14S)-hydroxy-(4Z,7Z,9E,11E,16Z,19Z)- docosahexaenoate, MCTR1) and other gamma-glutamyl compounds (such as leukotriene C4, LTC4). The metabolism of glutathione by GGT1 releases free glutamate and the dipeptide cysteinyl-glycine, which is hydrolyzed to cysteine and glycine by dipeptidases. In the presence of high concentrations of dipeptides and some amino acids, can also catalyze a transpeptidation reaction, transferring the gamma-glutamyl moiety to an acceptor amino acid to form a new gamma-glutamyl compound. Contributes to cysteine homeostasis, glutathione homeostasis and in the conversion of the leukotriene LTC4 to LTD4. [Isoform 3]: Seems to be catalytically inactive.
Synonyms: GGT 1; CD224; GGT; D22S672; D22S732; GGTD; GTG
Tractability: Small molecule: a structure with a bound ligand is known; a high-quality ligand is known. Antibody: UniProt places it where antibodies can reach, with high confidence; its Gene Ontology location is reachable by antibodies, with high confidence; UniProt predicts a signal peptide or a membrane-spanning region. PROTAC: ubiquitination databases record sites on it; its protein half-life has been measured; a small molecule that binds it is known.
Target class: Enzyme
Gene: Protein-coding gene on chromosome 22 (24,594,684 to 24,629,011, forward strand). Ensembl gene ENSG00000100031.
Subcellular location: Cell membrane
Subcellular location (Human Protein Atlas): Vesicles
Pathways (Reactome):
Disease: Defective GGT1 causes GLUTH; Defective GGT1 in aflatoxin detoxification causes GLUTH; LTC4-CYSLTR mediated IL4 production
Metabolism: Aflatoxin activation and detoxification; Glutathione synthesis and recycling; Synthesis of Leukotrienes (LT) and Eoxins (EX)
Drug ADME: Paracetamol ADME
Gene Ontology:
Molecular function: glutathione hydrolase activity; leukotriene-C(4) hydrolase; peptidyltransferase activity; protein binding
Biological process: amino acid metabolic process; fatty acid metabolic process; glutamate metabolic process; glutathione catabolic process; leukotriene D4 biosynthetic process; leukotriene metabolic process; proteolysis; zymogen activation; cysteine biosynthetic process; glutathione biosynthetic process; peptide modification; regulation of immune system process; regulation of inflammatory response; spermatogenesis; glutathione metabolic process
Cellular component: extracellular exosome; extracellular region; plasma membrane
Genetic constraint (gnomAD): Loss-of-function variants: 21 observed, 52.65 expected, observed/expected ratio (o/e) 0.4, 90% interval 0.28 to 0.57. The synonymous counts are far from expectation, so gnomAD's model fits this gene poorly and the ratio says little. Missense variants: 465 observed, 727.16 expected, observed/expected ratio (o/e) 0.64, 90% interval 0.59 to 0.69. Synonymous variants: 238 observed, 311.5 expected, observed/expected ratio (o/e) 0.76, 90% interval 0.69 to 0.85.
Homologues: Orthologues: macaque GGT1 (96% identical), dog GGT1 (84% identical), rat Ggt1 (79% identical), mouse Ggt1 (79% identical), zebrafish ggt1a (60% identical), zebrafish ggt1b (57% identical), tropical clawed frog ggt1 (55% identical), zebrafish ggt1l2.2 (50% identical), zebrafish ggt1l2.1 (48% identical), zebrafish si:dkey-222h21.12 (46% identical), zebrafish si:ch73-236c18.3 (46% identical), zebrafish si:ch73-59p9.2 (45% identical), and 3 more. Paralogues in human: GGT5 (41% identical), GGTLC1 (38% identical), GGTLC3 (37% identical), GGTLC2 (35% identical), GGT7 (30% identical), GGT6 (21% identical).
Diseases named in the same sentence as GGT1 in open-access papers:
GGT1 is named in the same sentence as 82 diseases in open-access papers, as found by Europe PMC text mining. Sharing a sentence is not in itself a finding about the gene and the disease. The quoted sentences say what the papers report.
prostate carcinoma (9 papers, 2017 to 2025). A carcinoma that arises from epithelial cells of the prostate gland. "GGT1 protein levels in exosomes were significantly higher in aggressive C4-2B cells compared to less aggressive LNCaP cells, suggesting that GGT1 expression is associated with disease progression in prostate cancer." (PMID 40094020, 2025). "In human prostate cancers, higher GGT1-derived γ-glutamyltransferase activity was recently reported in exosomes isolated from patient blood samples compared to benign prostatic hypertrophy (BPH) individuals." (PMID 40094020, 2025). "In conclusion, GGT1/GGT5 expression was upregulated but GGT6/GGT7 expression was downregulated in primary prostate cancers." (PMID 40094020, 2025). "PSA, CD9, and gammaglutamyltransferase 1 (GGT1), a cell-surface enzyme, isolated from human serum resulted in significantly higher prostatic cancer (PC) than in benign prostatic hypertrophy (BPH) patients." (PMID 31935918, 2020). "In addition, serum exosomal GGT1 can be used as a marker for the clinical features of advanced renal carcinoma, and a similar pattern was observed in prostate cancer, where serum exosomal GGT1 activity was significantly greater in malignant patients than in patients with benign hyperplasia." (PMID 41316810, 2025). "GGT1 expression and serum exosomal GGT activity were considerably greater in prostate cancer (PCa) patients than in benign prostatic hyperplasia (BPH) individuals." (PMID 40305328, 2025). "Our results showed that GGT1/5/6/7 genes are the predominant isoforms while GGTLC1/2/3 is expressed at a very low level in prostate tissues, although there are some outliers with higher levels of GGTLC2 in primary prostate cancers." (PMID 40094020, 2025). "Our results showed very strong negative correlations between the expression levels of GGT1/GGT5/GGT6 genes, and their DNA methylation levels in prostate cancer tissues." (PMID 40094020, 2025).
breast carcinoma (6 papers, 2010 to 2025). "High GGT1 levels are positively associated with a poor prognosis in breast cancer." (PMID 38523299, 2024). "The GGT1 gene SNPs might be an independent risk factor for poor response of NAC in breast cancer patients, providng theoretical basis for further precision therapy." (PMID 37891571, 2023). "Our finding revealed that local anesthetic ropivacaine attenuated breast cancer stemness through AKT1/GGT1/NF-κB signaling pathway, suggesting the potential clinical value of ropivacaine in breast cancer treatment." (PMID 38523299, 2024). "In this study, we identified GGT1 as the ropivacaine-regulated gene in breast cancer cells and subsequently demonstrated that GGT1 depletion abrogated CSC-like phenotypes, both in vitro and in vivo." (PMID 38523299, 2024). "Collectively, these results highlight the role of GGT1 in maintaining stem-like phenotypes of breast cancer." (PMID 38523299, 2024). "Kaplan–Meier survival analysis displayed that breast cancer patients with high level of GGT1 exhibited a shorter overall survival, compared with patients with lower levels of GGT1." (PMID 38523299, 2024). "To elicit the signaling pathways affected by GGT1 in the regulation of breast cancer stem cell-like phenotypes, we conducted RNA-seq analysis in GGT1-depleted MCF-7 cells (shGGT1) and control cells." (PMID 38523299, 2024). "Collectively, these results suggest elevated GGT1 predicts poor prognosis of breast cancer patients." (PMID 38523299, 2024). "In conclusion, our work suggests that ropivacaine functions as an AKT1-specific inhibitor, suppressing CSC-like phenotypes in breast cancer cells by inhibiting the NF-κB/GGT1 positive feedback loop." (PMID 38523299, 2024). "Analysis of GGT1 RNA levels in breast cancer tissue samples from the TCGA datasets revealed higher GGT1 expression compared to normal tissue." (PMID 38523299, 2024). "Based on the essential role of NF-κB signaling pathway in maintaining stemness of breast cancer cells, we thereby propose GGT1 activates NF-κB signaling pathway in breast cancer cells." (PMID 38523299, 2024). "Nevertheless, it is necessary to expand the number of the samples or to conduct multi-center prospective studies in the future, so as to better verify the predictive value of GGT1 gene varieties in NAC of breast cancer." (PMID 37891571, 2023). "This study represents a step forward toward a better understanding of the effect of GGT1 gene in breast cancer, providing a theoretical and clinical basis for individualized treatment." (PMID 37891571, 2023). "Three SNP loci (rs8135987, rs5751901, rs2017869) of GGT1 gene were selected and tested among breast cancer patients reciving NAC." (PMID 37891571, 2023). "We conclude that breast cancers occurring in women with Cowden disease commonly show apocrine differentiation and that GGT1 appear to be a useful marker to identify molecular apocrine carcinomas." (PMID 20712882, 2010). "Compared to HMEC-hTERT cells, GGT1 expression levels were higher in 6 breast cancer cell lines." (PMID 38523299, 2024). "Limited dilution analysis was also conducted to determine whether GGT1 mediated tumorigenesis of breast cancer cells." (PMID 38523299, 2024). "The GGT1 gene SNPs might be a novel biomarker of the sensitivity of NAC in breast cancer patients, providing theoretical basis for further precision therapy." (PMID 37891571, 2023). "However, the specific role of GGT1 in breast cancer progression remains largely unexplored." (PMID 38523299, 2024).
breast carcinoma (continued). "We performed a study to demonstrate whether the SNPs located in GGT1 gene had an effect on serum GGT protein level and the susceptibility of breast cancer patients undergoing neoadjuvant chemotherapy, in order to find out a genetic marker in predicting NAC sensitivity." (PMID 37891571, 2023). "GGT1 has a suggested function in pancreatic carcinogenesis, whereas NCOR1 is part of a corepressor complex with histone deacetylase 3 (HDAC3) and may act as an oncogene in thyroid cancer, while ERCC5 polymorphisms were reported in breast cancer." (PMID 35205822, 2022). "Depletion of GGT1 diminished stem phenotypes of breast cancer cells, indicating the formation of NF-κB /AKT1/GGT1/NF-κB positive feedback loop in the regulation of ropivacaine-repressed stemness in breast cancer cells." (PMID 38523299, 2024). "Here, we demonstrated that ropivacaine significantly suppressed the stemness and chemoresistance in breast cancer cells by serving as the AKT1 specific inhibitor and subsequent repressing the expression of GGT1." (PMID 38523299, 2024). "GGT1 (22q11.23), which is the most extensively studied gene, is highly expressed in renal cell carcinoma (RCC), hepatocellular carcinoma (HCC), gastric cancer (GC), and breast cancer (BRC) and is correlated with poor prognosis and metastasis." (PMID 41316810, 2025). "The prognosis of breast cancer patients with negative GGT1 expression was better than that of breast cancer patients with positive GGT1 expression." (PMID 35387129, 2022). "Based on these premises, we tested a hypothesis that GGT1 gene SNPs might affect the level of GGT protein in tissues and serum, which would, in turn, affect the efficacy and toxicity of neoadjuvant chemotherapy in breast cancer." (PMID 37891571, 2023).
diabetes (5 papers, 2015 to 2023). "We herein present for the first time the significant interactive effects of a GGT1 variant, rs4820599, and low HDL-C on a high pulse wave velocity (PWV), a surrogate marker of arterial stiffness, and DR in Japanese subjects with type 2 diabetes mellitus (T2DM)." (PMID 25952030, 2015). "The GGT1 G allele was significantly associated with the risk of a high baPWV (≥1,750 cm/sec) in the T2DM subjects (OR 1.80, P = 0.008), in addition to age, hypertension, the diabetes duration, low HDL-C (<1.0 mmol/L) and drinking in the univariate models." (PMID 25952030, 2015). "Moreover, we find CRP, GGT1, GPT, and GDF15 to be highly enriched for multiple disease terms related to cardiovascular diseases and diabetes in the GLAD4U disease database." (PMID 37590326, 2023).
type 2 diabetes (5 papers, 2011 to 2023). "A few studies have been done to assess the relationships between the SNPs of GGT1 gene and the risk of type 2 diabetes." (PMID 36902173, 2023). "In conclusion, our observed decrease in whole blood GGT1 mRNA levels along with decreased FPG levels after bariatric surgery in the current study are consistent with these prior studies that showed increased serum GGT activity in those at most risk for type 2 diabetes." (PMID 21423737, 2011).
asthma (4 papers, 2011 to 2024). "GGT1 overexpression has been implicated in various human diseases, including asthma, reperfusion injury, and cancer." (PMID 38233749, 2024). "Overexpression of γ-glutamyl transpeptidase (GGT1) has been implicated in an array of human diseases including asthma, reperfusion injury, and cancer." (PMID 33187988, 2021). "Overexpression of GGT1 contributes to the severity of a variety of pathological conditions including asthma, reperfusion injury, and cardiovascular disease." (PMID 33187988, 2021). "Based on our results simvastatin and perhaps more selective inhibitors of GGT1 could be considered as potential therapeutic tools to modulate airway wall fibrosis in fibrotic airway diseases such as asthma." (PMID 21864337, 2011).
clear cell renal cell carcinoma (4 papers, 2021 to 2025). "Studies have shown that GGT1 is involved in the development of clear cell renal cell carcinoma by promoting tumor cell migration and that the inhibition of GGT1 significantly attenuates migration, suggesting its therapeutic potential." (PMID 41316810, 2025). "For example, in clear cell renal cell carcinoma (ccRCC), GGT1 can maintain the level of intracellular GSH in ccRCC cells, protect against oxidative stress, and inhibit lipid peroxidation and iron death." (PMID 41316810, 2025). "Inhibiting the function of GGT1 can significantly inhibit the metastasis of renal clear cell carcinoma and improve the sensitivity to chemotherapy." (PMID 35387129, 2022). "GGT1 could promote the initiation and progression of clear-cell renal cell carcinoma." (PMID 34513707, 2021).
pancreatic cancer (4 papers, 2014 to 2019). "Similarly, GGT1 is implicated in pancreatic cancer by genome-wide association studies while AQP5 and CABLES1 enhance tumour progression." (PMID 25944692, 2015). "A genome-wide analysis of pancreatic cancer implicated GGT1 as playing a role in carcinogenesis." (PMID 25157234, 2014).
hepatocellular carcinoma (3 papers, 2021 to 2025). A malignant tumor that arises from hepatocytes. "In hepatocellular carcinoma, GGT1 expression has been positively correlated with the level of infiltration of CD4+ T cells, macrophages, and dendritic cells." (PMID 35387129, 2022).
lung cancer (3 papers, 2021 to 2025). A malignant neoplasm involving the lung. "GGT1 is highly expressed in the A549 lung adenocarcinoma cell line and its expression increases after IL‐1β stimulation, which rapidly converts LTC4 to LTD4, and GGT1 shows an important role in the development of resistance to erlotinib in non‐small cell lung cancer (NSCLC) cells." (PMID 41316810, 2025). "Additionally, in lung cancer models, GGT1 promoted the metabolism of LTC4 to LTD4, which could promote lung inflammation and tumorigenesis." (PMID 35387129, 2022). "mRNA transcripts of GGT-1, LTC4, FECR1, FECR2, miR-106b, ALDOA, ALDH3A1, and other genes in exosomes derived from lung cancer cells act as important regulators by playing an enabling role in promoting the invasion and migration of lung cancer cells." (PMID 34511114, 2021).
myocardial infarction (3 papers, 2014 to 2025). Gross necrosis of the myocardium, as a result of interruption of the blood supply to the area, as in coronary thrombosis. "Numerous studies have shown that high levels of GGT1 are associated with cardiovascular risk, heart failure, and myocardial infarction, which is consistent with the findings of this study." (PMID 40438595, 2025). "In contrast, VEGFA (0.919; 0.847–0.998; P = 0.044), KIT (0.754; 0.575–0.988; P = 0.041), TNF (0.881; 0.796–0.974; P = 0.014), CTNNB1 (0.920; 0.858–0.986; P = 0.018), and GGT1 (0.887; 0.796–0.989; P = 0.030) were associated with lower risk of myocardial infarction." (PMID 41573742, 2025). "Future in vivo studies using myocardial infarction animal models are therefore essential to confirm whether Quercetin truly exerts cardioprotective effects by modulating VEGFA, PTK2, and GGT1, as predicted in our bioinformatic and molecular docking analyses." (PMID 41573742, 2025).
renal fibrosis (3 papers, 2021 to 2024). A final common manifestation of a wide variety of chronic kidney diseases characterized by glomerulosclerosis and tubulointerstitial fibrosis. "Renal fibrosis in wild type and PT-Sirt6KO (Sirt6flox/flox; Ggt1-Cre+) mice was induced by UUO surgery." (PMID 35563783, 2022). "Based on the analysis of specific genes expressed in cisplatin-induced renal fibrosis, ACAT1, GGT1, and PDK2 were predominantly expressed in tubule cells." (PMID 34777334, 2021).
triple-negative breast carcinoma (3 papers, 2022 to 2024). An invasive breast carcinoma which is negative for expression of estrogen receptor (ER), progesterone receptor (PR), and human epidermal growth factor receptor 2 (HER2). "Recently, Li found that increased expression of GGT1 in triple negative breast cancer caused cisplatin resistance by affecting the hepatic leukemia factor (HLF), a process that may be closely linked to IL-6 levels in the immune microenvironment." (PMID 35387129, 2022). "Then, HLF promotes GGT1 to increase ferritin resistance, which fuels triple-negative breast cancer cell proliferation, metastasis, and cisplatin resistance." (PMID 38577592, 2024).
kidney stone (2 papers, 2025). "Genes associated with the identified metabolites (e.g., CLDN10, OGFOD2, and GGT1) were found to have causal links to kidney stone formation." (PMID 40842671, 2025). "Concurrently, six protein ratio pairs were found to inhibit kidney stone occurrence: GGT1/MME protein level ratio, ACE2/MME protein level ratio, ITIH3/VCAM1 protein level ratio, GZMA/TNFRSF8 protein level ratio, CRADD/HSPA1A protein level ratio and GZMA/TNFRSF4 protein level ratio." (PMID 40673688, 2025). "Five of these protein ratio pairs positively promote kidney stone development: BAIAP2/MME protein level ratio, GRPEL1/MME protein level ratio, HLAE/IL15 protein level ratio, CEACAM1/GGT1 protein level ratio and BTN2A1/IL18BP protein level ratio." (PMID 40673688, 2025).
melanoma (2 papers, 2020 to 2022). A malignant, usually aggressive tumor composed of atypical, neoplastic melanocytes. "The specific ability of GGT1 to cleave the gamma-glutamyl residue can in fact be exploited to activate glutathionylated pro-drugs, a pharmacologic strategy whose efficacy was documented in melanoma cells treated with the anti-angiogenic agent GSAO." (PMID 35669424, 2022).
osteoporosis (2 papers, 2016 to 2025). A condition of reduced bone mass, with decreased cortical thickness and a decrease in the number and size of the trabeculae of cancellous bone (but normal chemical composition), resulting in increased fracture incidence. "The function of GGT1 gene in humans is not well understood, but mutation of GGT1 gene in rats has been found to promote the development of osteoclasts and increase bone resorption, resulting in osteoporosis." (PMID 40943102, 2025). "GGT1 is an activator of TLR4-mediated osteoclastogenesis, and GGT1 is overexpressed in transgenic mice exhibiting symptoms of osteoporosis." (PMID 40943102, 2025).
ovarian carcinoma (2 papers, 2022 to 2023). A malignant neoplasm originating from the surface ovarian epithelium. "Ovarian cancers overexpressing GGT1 showed greater resistance to chemotherapy, especially cisplatin and 5-fluorouracil." (PMID 35387129, 2022).